AURKA (aurora kinase A)
Diseases named in the same sentence as AURKA in open-access papers (continued):
Sharing a sentence is not in itself a finding about the gene and the disease.
esophageal squamous cell carcinoma (8 papers, 2012 to 2025). Esophageal squamous cell carcinoma (ESCC) is a type of esophageal carcinoma (EC) that can affect any part of the esophagus, but is usually located in the upper or middle third. "In addition, knockdown of AURKA can enhance the ferroptosis effect of esophageal squamous cell carcinoma cells." (PMID 39944135, 2025). "In addition to GSK3β-mediated β-catenin regulation, AURKA also directly binds β-catenin in esophageal squamous cell carcinoma (ESCC) cells." (PMID 39334449, 2024). "For example, AURKA mediated esophageal squamous cell carcinoma progression through PI3K/AKT." (PMID 36973424, 2023). "In addition, it has been reported that the high expression of Aurora Kinase A in esophageal squamous cell carcinoma could significantly promote the proliferation of tumor cells and increase the resistance to apoptosis induced by DDP and ultraviolet radiation." (PMID 22809428, 2012).
Ewing sarcoma (8 papers, 2010 to 2025). A small round cell tumor that lacks morphologic, immunohistochemical, and electron microscopic evidence of neuroectodermal differentiation. "Overall, we identified a novel combination of mitotic inhibitors targeting KIF11 and AURKA that is highly synergistic in inhibiting the growth of an aggressive tumor such as Ewing sarcoma." (PMID 37894278, 2023). "In addition, studies by Huimou Chen and others have reported that AURKA induces apoptosis and ferroptosis in Ewing’s sarcoma cells through the NPM1/YAP1 axis." (PMID 38673957, 2024). "Researchers found that Aurora kinase A (AURKA) induced apoptosis and ferroptosis in Ewing’s sarcoma cells by inhibiting the NPM1/YAP1 axis, suggesting that AURKA may be a potential target for Ewing’s sarcoma." (PMID 39314848, 2024). "This study identified a synergistic combination of inhibitors for KIF11 (SB-743921) and AURKA that demonstrated significant pre-clinical activity in vitro and efficacy in an in vivo xenograft mouse model of Ewing sarcoma." (PMID 37894278, 2023). "In some other studies, kinases such as JNK, TOPK, AURKA, AURKB and LYN have all been studied in Ewing's sarcoma." (PMID 20718987, 2010). "For example, AURKA abundance was not particularly high in the Ewing sarcoma line SK-ES-1, but AURKA activity was high, as evidenced by the high ranks of AURKA substrates (Fig. EV3C)." (PMID 38177929, 2024). "The siRNA against LYN, TOPK and JNK did not affect Ewing's sarcoma cell proliferation while siRNA against AURKA had only a marginal effect." (PMID 20718987, 2010).
lymphoma (8 papers, 2015 to 2025). A malignant (clonal) proliferation of B- lymphocytes or T- lymphocytes which involves the lymph nodes, bone marrow and/or extranodal sites. "Additionally, high risk lymphomas rely on AURKA and PLK1 to sustain the high rate of proliferation." (PMID 33928032, 2021). "Although AURKA inhibitors have moved to phase III clinical trials in lymphomas, there has been slower progress in GI cancers and solid tumors." (PMID 25987188, 2015). "In CTCLs, the overexpression of AURKA and the hyperactivation of its downstream target polo-like kinase 1 (PLK1) accelerate mitotic entry of DNA-damaged cells favoring the accumulation of genomic aberrations in this lymphoma." (PMID 33928032, 2021). "Alisertib a selective small molecule against AURKA have been tested in clinical trials in lymphomas without reaching impressive results (#NCT01482962)." (PMID 33928032, 2021).
oral squamous cell carcinoma (8 papers, 2011 to 2025). "A recent study has demonstrated that AURKA SNPs (rs1047972 and rs2273535) increase the risk of oral squamous cell carcinoma." (PMID 29678897, 2018). "Moreover, the coexistence of betel nut chewing and AURKA SNPs is associated with the development of oral squamous cell carcinoma." (PMID 33050100, 2020). "We found that the inhibition of the CBP/β-catenin axis mediated by ICG-001 in oral squamous cell carcinoma led to the downregulation of BIRC5, EZH2, AURKA, CCNA2, and other genes previously implicated in therapy resistance." (PMID 41227355, 2025). "Also, in oral squamous cell carcinoma (OSCC) with aberrant expression of serine-threonine protein kinase A (AURKA), the knockdown of AURKA can increase ROS levels and inhibit EMT." (PMID 38474405, 2024).
adrenocortical carcinoma (7 papers, 2020 to 2024). "AURKA is also identified as a prognostic ferroptosis-related gene signature in adrenal cortical carcinoma." (PMID 38673957, 2024). "Blocking the β-catenin pathway and inhibiting AURKA activity at the same time may enhance antitumor response in adrenocortical cancer." (PMID 34336648, 2021). "In comparison to normal adrenal tissues, AURKA and AURKB expression was upregulated in adrenocortical carcinoma and three cell lines (CU-ACC1, CU-AAC2, and NCI-H295R), while no discernible differences were observed for AURKC." (PMID 38269250, 2023).
brain tumors (7 papers, 2012 to 2024). "Targeting AURKA represents a promising cancer treatment strategy for brain tumors, particularly due to small molecule inhibitors like Alisertib that can penetrate the blood–brain barrier." (PMID 38995006, 2024). "Among these kinases is aurora kinase A (AURKA), a target we have recently shown to have therapeutic value in several brain tumors." (PMID 22390279, 2012).
colorectal adenoma (7 papers, 2016 to 2023). An adenoma that arises from the colon or rectum. "In CRC, AURKA is critical for chromosome 20q amplification‐associated malignant transformation in colorectal adenomas." (PMID 31087508, 2019). "The AURKA and TPX2 genes are also related to carcinogenesis in CRC by promoting the progression of colorectal adenoma to colorectal adenocarcinoma." (PMID 34070979, 2021).
gastric tumor (7 papers, 2014 to 2025). "AURKA mRNA was significantly elevated in gastric tumor tissue samples, as compared with normal tissues (P < 0.001)." (PMID 31740746, 2019). "Consistently, we found a higher AURKA expression in gastric tumor tissues compared with their adjacent normal tissues." (PMID 28218735, 2017). "In addition, AURKA SNP rs2273535 significantly increased the risk of gastric tumors, particularly in female patients and nonsmokers." (PMID 33050100, 2020). "The violin plot showed that the expression levels of the AURKA, CEP55, DTL, and TTK genes were significantly increased in colorectal and gastric tumor tissues (p value < 0.05)." (PMID 40723362, 2025). "In the immunohistochemically validated cohort, aurora kinase A (AURKA) expression was significantly higher in nongastric tumors than in gastric tumors and was significantly correlated with Armed Forces Institute of Pathology-Miettinen risk group." (PMID 25264210, 2014).
pancreatic adenocarcinoma (6 papers, 2012 to 2026). "Compared with normal tissues, most tumor types show significantly higher expression of AURKA, except for pancreatic adenocarcinoma (PAAD), PCPG, skin cutaneous melanoma (SKCM), and thymoma (THYM)." (PMID 33451333, 2021). "However, combined inhibition of AURKA and the mammalian target of rapamycin yielded limited clinical benefit in patients with refractory solid tumors, including pancreatic adenocarcinoma." (PMID 41562677, 2026).
prostate tumors (6 papers, 2007 to 2023). "Data from TCGA databases suggested that SNHG4 expression was significantly correlated with the expression of RRM2, EZH2, AURKA and TK1 in prostate tumor samples (p < 0.01)." (PMID 37596700, 2023). "AURKA levels are considerably increased in prostatic intraepithelial neoplasia (PIN) lesions and prostate tumors as compared to its levels in non-neoplastic specimens." (PMID 33158056, 2020).
psoriasis (6 papers, 2022 to 2024). An autoimmune condition characterized by red, well-delineated plaques with silvery scales that are usually on the extensor surfaces and scalp. "Aurora kinase A (AURKA) promotes psoriasis-associated inflammation by blocking autophagy-mediated inhibition of AIM2 inflammatory vesicles." (PMID 39559368, 2024). "One study found that AURKA is highly expressed in psoriasis tissues and can promote the occurrence of psoriasis-related inflammation by blocking the autophagy-mediated AIM2 inflammasome." (PMID 39045407, 2024). "TOP2A and AURKA genes also play important roles in psoriasis and may serve as molecular targets for precision therapy, providing new directions for further research into their mechanisms." (PMID 38382096, 2024). "Recent studies have found that certain factors regulate the AIM2 inflammasome signaling pathway and participate in the pathogenesis of psoriasis, including prokineticin 2 (PK2), caspase recruitment domain family member 18 (CARD18), aurora kinase A (AURKA), TLR-7, TLR-8, and TLR-9 antagonists." (PMID 36118867, 2022).
viral infection (6 papers, 2016 to 2025). "For example, genes such as AURKA and CDK1 have been previously implicated in cell cycle regulation during viral infections, consistent with our results." (PMID 40100920, 2025). "In addition to apoptotic stimuli, AURKA is cleaved in response to viral infection." (PMID 38994036, 2024). "Apoptotic stimuli lead to Asp132-cleavage of AURKA in various human cancer cell lines, regardless of viral infection." (PMID 38994036, 2024). "To investigate whether Asp132-cleavage of AURKA in STS-induced cell apoptosis is affected by viral infection, we examined the cleavage of AURKA in both non-viral (DG75 and iSLK) and viral (BC3, B95.8, and iSLK-16) cancer cells treated with STS at different time points." (PMID 38994036, 2024). "Asp132-cleavage of AURKA was observed in all cells following apoptotic stimuli, indicating that cleavage of AURKA at Asp132 during STS-induced apoptosis does not depend on viral infection." (PMID 38994036, 2024).
adenoma (5 papers, 2008 to 2021). A neoplasm arising from the epithelium. "Further progression from adenoma-to-carcinoma is frequently associated with 20q gain and overexpression of Aurora kinase A (AURKA)." (PMID 29760449, 2018). "Using the Sengenics CTA protein array, pooled benign controls (n = 2, adenomas) showed detectable autoantibodies (Z-score > 3) against five antigens (AURKA, CTAG1A, CYP450 3A4, MAGEA4 and RAF1)." (PMID 34681879, 2021).
chondrosarcoma (5 papers, 2012 to 2022). A malignant cartilaginous matrix-producing mesenchymal neoplasm arising from the bone and soft tissue. "The expression of Aurora Kinase A and B was significantly higher in chondrosarcoma than in chondroma (p < 0.01)." (PMID 28439237, 2017). "Another promising marker is Aurora Kinase A and B that has proven to be correlated with poor outcome in patient with chondrosarcoma." (PMID 24667142, 2014). "The positive ratio of Aurora Kinase A was significantly higher in chondrosarcoma than that in chondroma tissues (p<0.01)." (PMID 22809428, 2012). "The expression of Aurora Kinase A and B were significantly lower in group low grade conventional chondrosarcoma than that in groups medium and high grade conventional chondrosarcoma (p<0.01)." (PMID 22809428, 2012). "Which demonstrate that Aurora Kinase A and B play an important role in the formation and development of chondrosarcoma." (PMID 22809428, 2012). "The Aurora Kinase A protein was observed mainly in the cytoplasm, and it was positive in 45 of the 72 patients (62.5%) with chondrosarcoma and in 6 of the 42 cases (14.3%) with chondroma." (PMID 22809428, 2012). "In this report, we investigated the expression of Aurora Kinase A and B in chondrosarcoma and provided a strong support for the development of the new drugs of molecular targeted therapy for chondrosarcoma." (PMID 22809428, 2012). "Our study found that the expression of Aurora Kinase A and B was significantly up-regulated in chondrosarcoma, and the expression of Aurora Kinase A and B was correlated with the recurrence and metastasis of chondrosarcoma." (PMID 22809428, 2012). "The expression of Aurora Kinase A and B in chondrosarcoma was significantly higher than that in chondroma (p<0.01)." (PMID 22809428, 2012). "Both the Aurora Kinase A and B might involve in the oncogenic, invasive and metastatic process of chondrosarcoma; however, the mechanism is still unclear." (PMID 22809428, 2012). "The expression of Aurora Kinase A and B in chondrosarcoma showed a positive correlation (p<0.01)." (PMID 22809428, 2012). "The Aurora Kinase A and B could be used as a new prognostic marker and molecular therapeutic target for chondrosarcoma." (PMID 22809428, 2012). "In the further study, we will further conduct related experiments to identify whether the Aurora Kinase A inhibitor can be used as the molecular target treatment for chondrosarcoma." (PMID 22809428, 2012). "Accordingly, Aurora Kinase A is expected to become the new target for chondrosarcoma." (PMID 22809428, 2012). "Our results showed that the expression of Aurora Kinase A was very low in chondroma tissues, while it was strongly expressed in chondrosarcoma; which indicated that Aurora Kinase A played an important role in the initial and developmental stage of the chondrosarcoma." (PMID 22809428, 2012). "Whether the Aurora Kinase A and B were expressed in the chondrosarcoma is still unknown, in this study, we investigated the expression of the Aurora Kinase A and B in the chondrosarcoma tissues by immunohistochemistry and analyzed its clinical significance; and we also followed-up the patients." (PMID 22809428, 2012). "The results of Kaplan-Meier survival analysis showed that chondrosarcoma patients who had a positively expressed Aurora Kinase A had a relatively poor prognosis (p<0.05) which indicates that the Aurora Kinase A might be a prognostic marker for the chondrosarcoma." (PMID 22809428, 2012). "Therefore, Aurora kinase A can be used to predict the prognosis of patients with chondrosarcoma." (PMID 22809428, 2012). "There were differences about the expression of Aurora Kinase A and B in chondrosarcoma between the recurrence group and the non-recurrence group, metastatic group and non-metastatic group (p<0.05), but not age and gender (p>0.05)." (PMID 22809428, 2012).
liposarcoma (5 papers, 2014 to 2022). A usually painless malignant tumor that arises from adipose tissue. "Selinexor decreased aurora kinase A and B levels in these cells and inhibitors of these kinases suppressed the growth of the liposarcoma cells." (PMID 27893412, 2017). "These genes include ZIC1, TOP2A, and AURKA, which have high expression levels across the liposarcoma spectrum." (PMID 25238053, 2014). "Overall, our study showed that selinexor treatment restored tumor suppressive function of IGFBP5 and inhibited aurora kinase A and B in liposarcoma cells supporting the usefulness of selinexor as a potential therapeutic strategy for the treatment of this cancer." (PMID 27893412, 2017). "Efforts made to define the molecular basis of liposarcomas lead to the finding that besides the amplifications of CDK4 and MDM2, Aurora Kinase A, also was shown to be overexpressed." (PMID 26887042, 2016).
neutropenia (5 papers, 2021 to 2024). A decrease in the number of neutrophils found in the blood. "This behavior is not influenced by the AURK isoform selectivity of the inhibitors as neutropenias were induced by both AURKA and AURKB selective inhibitors." (PMID 36224199, 2022). "Nearly fifty AURKA inhibitors are in clinical trials, but no AURKA-targeted drug has been approved yet, partly due to associated collateral toxicity including neutropenia, somnolence and mucisitis." (PMID 39334449, 2024).
Obesity (5 papers, 2021 to 2023). Accumulation of substantial excess body fat. "Loss of AURKA in the intestinal epithelia causes gut microbiota dysbiosis and higher levels of propionate, leading to Akt activation, which in turn promotes obesity." (PMID 36232337, 2022). "This suggests that forced elongation of primary cilia caused by AURKA inhibition may rectify the dysregulation of cell proliferation and/or differentiation caused by impairment of ciliogenesis in cancer and obesity." (PMID 34428960, 2021). "Using WGCNA, we confirmed AURKA, ITGB2, CTSS, and TYROBP as hub genes, which were identified in the coexpressed modules in PER♂, whereas AURKA was identified as a hub gene in PER♀, and these hub genes have been associated with obesity comorbidities." (PMID 37458462, 2023). "Although several preclinical studies supported AURKA as a therapeutic target for cancers, further studies are required to establish the role of AURKA in adipose development and its implication for obesity using an animal model on a large scale and in humans." (PMID 37458462, 2023). "In the remainder of this review, we focus on the association between AURKA (Section 2) and AKT (Section 3) and primary cilia function and how their dysregulation contributes to ciliopathies such as cancer and obesity." (PMID 34944109, 2021). "AURKA inhibitors, as well as Akt inhibitors, have been developed and evaluated in cancer and obesity." (PMID 34428960, 2021). "It is possible that AURKA might play different roles depending on the state of obesity, and density of mesenchymal stem cells in adipose tissues." (PMID 33975549, 2021). "Mesenchymal stem cells derived from adipose tissue of obese subjects exhibited shortened and deficient cilia, triggered by upregulation of ciliary disassembly regulators, like AURKA, resulting in a defect in adipogenesis, which in turn promoted adipocyte hypertrophy during the course of obesity." (PMID 33975549, 2021). "Several hub genes, such as TOP2A, CENPF, TYMS, AURKA, KIF4A, and KIF20A, are related to the cell cycle and DNA replication, implicating the close relationship between obesity and cancer." (PMID 36232337, 2022). "Some of the hub genes identified were AURKA, MELK, and TKT for prenatal LOW vs HIGH nutrition, and CTSS and ITGB2 for late gestation malnutrition followed by early obesity development (LOW-HCHF and HIGH-HCHF vs NORM-CONV)." (PMID 33975549, 2021). "Not surprisingly, dysregulation of this AURKA noncatalytic function is known to contribute to the development and progression of various diseases, including cancer and obesity." (PMID 34944109, 2021).
ovarian tumor (5 papers, 2010 to 2017). "Further, high levels of active AURKA in ovarian tumors are also associated with supernumerary centrosomes and overall decreased survival." (PMID 28881569, 2017). "Using an orthotopic mouse model, we reported that alisertib specifically inhibited AURKA activity in vivo and exerts ovarian tumor growth inhibition (TGI) as a single agent." (PMID 28881569, 2017). "Collectively, these observations suggest that AURKA inhibition decreases PARP expression and stimulates the NHEJ DNA repair pathway in PARPi-resistant ovarian tumor cells in vivo, consistent with our in vitro observations." (PMID 28881569, 2017). "The proliferation-related targets AURKA and CCNB1 were overexpressed in clinical ovarian tumor specimens." (PMID 26317392, 2015). "Likewise, genes frequently amplified (MYC, PIK3CA and AURKA) or lost (RB1, PTEN) in ovarian tumours were also commonly multiplied or lost in our set of patient cells." (PMID 29180611, 2017).